LINC01547 (long independently transcribed non-coding RNA 1547)
Synonyms: C21orf67; C21orf69; PRED54
Gene: Long non-coding RNA gene on chromosome 21 (44,932,814 to 44,939,951, reverse strand). Ensembl gene ENSG00000183250.
Diseases named in the same sentence as LINC01547 in open-access papers:
LINC01547 is named in the same sentence as 2 diseases in open-access papers, as found by Europe PMC text mining. Sharing a sentence is not in itself a finding about the gene and the disease. The quoted sentences say what the papers report.
tumor (2 papers, 2021 to 2024). "Linc01547 has been linked to autophagy in the tumor microenvironment." (PMID 39605035, 2024).
LINC01547 also shares sentences with these, for which no sentence is quoted: Cirrhosis (1 paper).